MIR126 (microRNA 126)
Synonyms: hsa-mir-126; MIRN126; miRNA126; mir-126
Gene: MicroRNA gene on chromosome 9 (136,670,602 to 136,670,686, forward strand). Ensembl gene ENSG00000199161.
Gene Ontology:
Cellular component: RISC complex
Homologues: Orthologues: chimpanzee ptr-mir-126 (100% identical), macaque mml-mir-126 (95% identical), dog MIR126 (84% identical), pig ssc-mir-126 (84% identical), guinea pig MIR126 (82% identical), mouse Mir126a (80% identical), tropical clawed frog xtr-mir-126 (73% identical), zebrafish mir126a (71% identical), zebrafish mir126b (71% identical).
Diseases named in the same sentence as MIR126 in open-access papers:
MIR126 is named in the same sentence as 5 diseases in open-access papers, as found by Europe PMC text mining. Sharing a sentence is not in itself a finding about the gene and the disease. The quoted sentences say what the papers report.
malignant mesothelioma (1 paper, 2016). A malignant neoplasm of the pleura or peritoneum, arising from mesothelial cells. "Previously we reported that MIR126 is downregulated in malignant mesothelioma (MM)." (PMID 27119351, 2016).
prostate carcinoma (1 paper, 2011). A carcinoma that arises from epithelial cells of the prostate gland. "The expression of MIR126* has been investigated in prostate cancer in two previous studies and the results from these studies correspond well with our results as the miRNA was downregulated in both studies." (PMID 21619623, 2011).
type 2 diabetes (1 paper, 2024). "A possible trend toward significance was found in the expression of the MIR126 gene (p = 0.051), the MIR133A1 gene (p = 0.076), the MIR143 gene (p = 0.08), and the MIR320A gene (p = 0.095) in patients with type 2 diabetes." (PMID 38256676, 2024).
cancer (3 papers, 2019 to 2023). A tumor composed of atypical neoplastic, often pleomorphic cells that invade other tissues. "Other genes, including GATA2, GADD45B, and MIR126, are differentially methylated in WD liver and blood, also play a role in epigenetic mechanisms in cancer." (PMID 30709419, 2019). "In estrogen receptor-positive cancer with mass lesion type, CCL3L1 (21-fold), SNHG12 (11-fold), and MIR206 (sevenfold) were upregulated, and MIR597 (265-fold), MIR126 (12-fold), and SOX17 (fivefold) were downregulated." (PMID 37391754, 2023). "The up-regulated in IPF is PRSS3, a well-known oncogene that promote cell migration and cancer metastasis, while the down-regulated in IPF is MIR126, which functions as a tumor suppressor that inhibit cell migration." (PMID 32244228, 2020).
MIR126 also shares sentences with these, for which no sentence is quoted: tumor (2 papers).